FAP (fibroblast activation protein alpha)
Diseases named in the same sentence as FAP in open-access papers (continued):
Sharing a sentence is not in itself a finding about the gene and the disease.
cancer (continued). "A marker that could be used to further characterize CAFs is fibroblast activation protein (FAP) that is also targeted for PET imaging of cancer." (PMID 39009951, 2024). "Interestingly, CAFs overexpress fibroblast activating protein (FAP), which is therefore abundant in many cancer histotypes." (PMID 38695960, 2024). "Moreover, FAP can also be expressed directly in a limited number of cancer cells, such as some ovarian, breast, an pancreatic cancers as well as in sarcomas, suggesting possible theranostic applications in the future." (PMID 40604259, 2024). "Radiolabeled FAPα inhibitors (68Ga-FAPI and 18F-FAPI) imaging by PET/CT have shown efficacy in labeling a wide range of solid carcinomas via interactions with cancer-associated fibroblasts, and may improve lesional localization and activity measurement in FD." (PMID 39273006, 2024). "FAP expression, noted in various cancers, often hints at prognosis." (PMID 38558814, 2024). "Considering the pivotal role of FAP in cancer, we analyze its expression across 23 cancers using the TCGA database, revealing significant upregulation in 16 cancer types (specially in HNSCC), downregulation in three cancer types, with no significant changes observed in the other four cancers." (PMID 38826849, 2024). "In the aspects of clinical values, FAP is a cell surface marker for these CAF subtypes in over 90% of human cancers, vaccination against the FAP antigen carried by these CAFs may be the ideal strategy for cancer immunotherapy." (PMID 38158643, 2024). "For example, FAP-specific drugs have the potential to efficaciously target lesions in cancers." (PMID 38459511, 2024). "This prompted us to delve deeper into the correlation between FAP overexpression on one side and the enrichment of major immune cell signatures along with the activation of metabolic pathways on the other side across an array of cancer types." (PMID 39035007, 2024). "FAPα+ cell targeting studies in cancer may help us exploring new strategies for targeting FAPα+ FLSs in RA." (PMID 38783357, 2024). "It is imperative that future studies focus on the potential benefits of increasing cytotoxic or radiotherapeutic drug concentrations near cancer cells through FAP targeting versus the costs of potentially depleting FAP+ stromal cells as a result of using FAP-targeting antibodies." (PMID 39335130, 2024). "Fortunately, early preclinical work appears to support that such antibody–drug conjugates may more selectively kill cancer cells than slower-growing FAP+ stromal cells." (PMID 39335130, 2024). "Together, these observations suggest that the bystander killing effector mechanisms operative in FAP‐CAR‐T cells may only be effective against cancer cells that express cognate receptors, whereas healthy cells lacking receptor expression are not targeted." (PMID 38975278, 2024). "The effectiveness of CAR T cell treatment may be increased by targeting FAP in addition to cancer antigen targets." (PMID 39281684, 2024). "Therefore, we performed a pan-cancer analysis and verified the potential carcinogenic effects of FAP in HNSC." (PMID 39055892, 2024). "Fibroblast activation protein (FAP), a serine protease and well-established CAF surface protein, is commonly overexpressed in activated fibroblasts and high expression is associated with worse survival in multiple cancer types." (PMID 38328551, 2024). "Given these past results FAP-targeting antibodies are being studied in conjunction with cytotoxic chemotherapy or radiotherapeutics, that may affect adjacent cancer cells." (PMID 39335130, 2024). "Several proof of principle study assays have been carried out to explore the capacity of FAPα as a local pro-drug activator of engineered cytotoxic pro-drugs for cancer treatment, including the combination with photoactivation in peptide-locked photosensitizers." (PMID 39273006, 2024).
cancer (continued). "Importantly, FAP+ CAF subpopulation accumulates in cancers with poor prognosis and has been shown to be involved in metastatic spread and cancer immunosuppression." (PMID 39239526, 2024). "FAP-targeted cancer therapy has garnered significant attention in recent years." (PMID 39519118, 2024). "Meanwhile, when RPT is directed at cells in the surrounding TME instead of directly targeting cancer cells, such as through FAP targeting, both 177Lu and 225Ac may exhibit reduced effectiveness in cancer cell-enriched areas." (PMID 39629134, 2024). "FAP is also detected in cancer cells, complicating its role as a biomarker." (PMID 38540204, 2024). "FAP is infrequently expressed in normal tissues but is prevalent in various malignant tumors." (PMID 39519118, 2024). "Nevertheless, the relationship between FAP expression and cancer is far from constant." (PMID 39035007, 2024). "As a result, quinoline-derived small-molecule inhibitors emerged as the most effective FAP inhibitors (FAPIs), and their uses have been advanced to FAP-targeted cancer imaging with positron emission tomography (PET) and single-photon emission computer tomography (SPECT)." (PMID 39766079, 2024). "By looking into the immune signatures associated with FAP+CAFs and its impact on the broader TME, our study aims to contribute to a more holistic understanding of the interplay between stromal elements, immune responses, and cancer cells." (PMID 39035007, 2024). "In addition, the number of interactions found between cancer cells and FAP+ CAF clusters by CellChat reflected their spatial proximity in the TME." (PMID 38561380, 2024). "Fibroblasts expressing fibroblast activation protein (FAP) are responsible for producing and organizing fibrous materials (such as fibronectin and collagen), thereby driving T cell marginalization and restricting their contact with cancer cells." (PMID 39107856, 2024). "FAPi PET could also be useful in identifying cancer patients who might benefit from anti-FAP therapy." (PMID 38275890, 2024). "Nevertheless, this result did not indicate the true functional significance of FAP in CAFs’ contribution to cancer survival because other CAFGs expressions synchronized with the FAP expression were also considered to be depleted in the diphtheria toxin experiments." (PMID 38892190, 2024). "Our findings highlight that targeting the circNOX4/miR-329-5p/FAP/IL-6 axis might be a novel strategy for cancer therapy in NSCLC." (PMID 38459511, 2024). "The FAP inhibitor (FAPI) is used as a probe to deliver nuclides to cancer tissues." (PMID 37240044, 2023). "As a consequence of promising results showed in clinical research studies, FAP-targeted imaging agents are currently evaluated in clinical trials for their efficiency and biosafety for the diagnosis of primary and metastatic lesions in various types of cancer." (PMID 36674595, 2023). "CXCL12/CXCR4 cascade in FAP+CAF also contributed to cancer cell proliferation." (PMID 37784082, 2023). "Additionally, PD-L1+ cancer cells were positively correlated with the expression of both αSMA and FAP." (PMID 37668710, 2023). "Furthermore, FAP protein, known as a specific biomarker for CAFs, was found to be expressed in various cancer cells and immune cells." (PMID 37490719, 2023). "However, the majority of research on the role of FAP in tumors has focused on a single type of cancer." (PMID 37490719, 2023). "Despite HCC being reported to exhibit a relatively low FAP expression and an intermediate level of mean SUVmax compared to other cancer types, FAPI PET has demonstrated promising outcomes for HCC primarily because of its minimal liver uptake, resulting in very low background activity." (PMID 37608378, 2023). "Membrane molecules LRRC15, ITGA11, SPHK1 and FAP could be used as therapeutic targets for CSF-targeting cancer treatment." (PMID 36744260, 2023).
cancer (continued). "Notably, high levels of expression of α-smooth muscle actin (αSMA) (p = 0.015) and fibroblast activation protein (FAP) (p = 0.048), which are known CAF markers, were also significantly associated with high IL-7R expression in cancer nests." (PMID 36672342, 2023). "Moreover, enhancing antitumor activity was possible by combining FAP-specific CAR-T cells with T cells targeting cancer cells themselves, suggesting the benefit of co-targeting both CAFs and cancer cells in solid tumors." (PMID 38516299, 2023). "Thus, we tried to decipher the miRNAs and lncRNAs of which were able to regulate FAP expression and further affect the cancer development." (PMID 37166418, 2023). "In terms of the correlation between FAP expression and the TME, ESTIMATE analysis reveals a significant positive connection between FAP expression and StromalScore in 33 types of cancer, ImmunScore in 28 types of cancer, and ESTIMATEScore in 32 types of cancer." (PMID 37490719, 2023). "One popular molecular target in the development of this therapy has been FAP, expressed on cancer-associated fibroblasts, but not in normal tissues." (PMID 37345192, 2023). "In combination, our pan-cancer solid tumor approach showed that overexpression of CXCR4 or FAP lead to detectable transcriptional changes (in terms of mRNA and miRNA), reflected by gene signatures best distinguishing high- and low-expressing samples in RF models." (PMID 36672341, 2023). "Additionally, we investigated the correlation of FAP expression with DNA methylation, immune infiltration levels in 36 cancers." (PMID 37490719, 2023). "In bladder cancer, FAP+ CAFs were associated with poor infiltration of CD8+ T cells with stromal changes and significant loss of human leukocyte antigen (HLA-I) expression in cancer cells." (PMID 37784082, 2023). "Fibroblast activation protein (FAP) is highly overexpressed in stromal tissue of various cancers." (PMID 36813980, 2023). "Furthermore, distinct signaling pathways and transcription factors that are active in each cancer type can regulate the expression of FAP." (PMID 37490719, 2023). "Monocytes are the main source of macrophages and FAP was found positively correlated to the infiltration of macrophages across all these cancers, suggesting that FAP may be involved in cancer immunology by regulating macrophages functions." (PMID 37325617, 2023). "Functional analysis indicated that the highly-expressed FAP in these cancers could affect extracellular matrix organization process and interacted with genes like COL1A1, COL1A2, COL3A1 and POSTN." (PMID 37325617, 2023). "As a result, cancer patients with high levels of FAP expression have worse clinical outcomes." (PMID 37316886, 2023). "In addition, in murine models of multiple human cancers, FAP-IL2v combined with various therapeutic antibodies has also shown some positive efficacies." (PMID 37784082, 2023). "It is presently hypothesized that FAP targeted radioligand therapy (TRT) may become a novel treatment for various types of cancer." (PMID 36813980, 2023). "Hence, we explored the relationship between FAP expression and patient prognosis based on the TCGA, cancer cell line encyclopedia (CCLE), GTEx databases." (PMID 37490719, 2023). "With regard to the urgent need for new strategies in cancer treatment, FAP may serve as a possible target for new diagnostics and targeted therapy of CRC in the near future." (PMID 37614665, 2023). "We analyzed the mRNA expression profile of FAP across diverse cancer types in TCGA using TIMER2.0." (PMID 37166418, 2023). "In addition, it was also observed that FAP was positively correlated to M2 macrophages infiltration across these cancers." (PMID 37325617, 2023). "As pan-cancer imaging agents, the recently introduced FAP ligands have opened a new avenue in the diagnosis of several epithelial malignancies known to overexpress FAP." (PMID 37345133, 2023).
cancer (continued). "Thus, in this study, we systematically evaluated the FAP expression profile across thousands of cancer cases based on the TCGA, GTEx and CPTAC datasets, to establish the link between FAP expression and the clinical prognostic features." (PMID 37166418, 2023). "Considering the current interest and therapeutic potential in targeting FAP as a cancer antigen and modulator of the TME, in this work, we aimed to develop TMs specifically binding to hFAP that could be used as theranostic tools." (PMID 38102692, 2023). "In seven types of cancer, FAP expression is positively correlated with DNA methylation." (PMID 37490719, 2023). "Another ongoing clinical trial (NCT04499365) plans to enroll 500 subjects for 68Ga-DOTA/NOTA-FAPI-04 PET to provide robust clinical evidence regarding the use of FAP-targeted imaging for the diagnosis of primary and metastatic lesions in various types of cancer." (PMID 36674595, 2023). "Through this study’s simple analysis, We can tentatively speculate that the overexpression of COL10A1/FAP/FN1 is positively correlated with cancer immunity." (PMID 38063927, 2023). "The 18 F-labeled FAPI targeted radioligand, 18 F-FAPI-42, has been reported following to exhibit comparable uptake in FAP-positive cells and tumors as 68Ga-FAPI-04, with numerous studies demonstrating its diagnostic efficacy in various cancers and fibrotic diseases." (PMID 37932744, 2023). "By targeting fibroblast-activated protein (FAP), which is also a marker for stromal cells, we may be able to efficiently target cancer tissues." (PMID 37240044, 2023). "FAP is highly expressed by fibroblasts in cancer stroma and by some cancer cells." (PMID 37818347, 2023). "Thus, our data suggest that the (2S,4S)-4-fluoropyrrolidine-2-carbonitrile scaffold holds potential as a promising pharmacophore for the design of FAP-targeted radioligands for cancer diagnosis and therapy." (PMID 37110717, 2023). "Targeting FAP to deplete stromal CAFs may also disrupt cancer supportive functions and inhibit PDAC growth." (PMID 38011131, 2023). "Cancer-activated fibroblasts express FAP and FAP is thus an important marker of CAFs." (PMID 37568769, 2023). "Importantly, FAP is involved in various pathological processes and can be detected in more than 90% of malignant epithelial tumors." (PMID 36831535, 2023). "FAP has emerged as a promising target for diagnosing and treating various malignant tumors." (PMID 38026901, 2023). "Nonetheless, given the ubiquitous presence of fibroblasts in cancer and the avidity of FAP-targeted imaging agents, FAP-targeted PET imaging has the potential to revolutionize the landscape of oncological PET/CT imaging and improve the clinical care of this highly problematic disease." (PMID 36674595, 2023). "FAP-targeted radiotherapy would not only impact immunosuppressive FAP-positive CAFs but also affect neighboring cancer and stromal cells in the TME through crossfire effects given the distance travelled by the average beta-particle emission from 177Lu (~ 100 cell diameters)." (PMID 37086273, 2023). "Furthermore, the DIA of TMA-based multiplex immunofluorescence staining revealed the protein co-expression relationship between PODNL1 and FAP, an important CAFs marker, in 20 types of cancer." (PMID 37504302, 2023). "Several strategies targeting FAP have been explored for cancer immunotherapy." (PMID 37818347, 2023). "Fibroblast activation protein (FAP) expressed on cancer-associated fibroblasts is a popular target expressed in cancer cells and not in normal cells." (PMID 37998743, 2023). "We demonstrated that CSFs could be potential targets for cancer treatment, and membrane molecules FAP, LRRC15, ITGA11 and SPHK1 could be used as CSFs specific targets." (PMID 36744260, 2023). "Our new-found ceRNA network provided a better understanding of the molecular mechanisms of FAP regulation, and indicated that FAP as well as the correlated miRNAs or lncRNAs may be promising targets or biomarkers in cancer therapy." (PMID 37166418, 2023).
cancer (continued). "Another promising approach is using cancer vaccines that successfully target FAP." (PMID 37316886, 2023). "As gastrointestinal cancers are increasingly prevalent in the world and possibly account for 20% of cancer cases, we suspected that FAP could be a potential gastrointestinal cancer biomarker and instructive for future treatment options." (PMID 37325617, 2023). "FAP is selectively expressed on the surface of CAFs in various types of cancer." (PMID 37490719, 2023). "POSTN+FAP+eCAFs are related to ICB resistance across cancers." (PMID 37199594, 2023). "Activation of FAP expression has been shown in inflammation and cancer." (PMID 36825204, 2023). "These metabolic data identify a previously unknown role of FAP-α in modifying cancer cell metabolism in the TNBC cell line studied here that may provide new insights into its functional roles in cancer progression." (PMID 36937451, 2023). "(R)-(((quinoline-4-carbonyl)-D-alanyl)pyrrolidin-2-yl)boronic acid is a highly promising pharmacophore that can be used to develop PET imaging agents with superior pharmacokinetics properties and excellent imaging contrasts for visualization of FAP-overexpressing carcinomas." (PMID 37375746, 2023). "Importantly, FAP is involved in various pathological processes and is selectively overexpressed in majority of tumors (over 90% of malignant epithelial tumors), making it a potential pan-cancer target." (PMID 38111465, 2023). "FAP has drawn considerable attention as a target enzyme in various fibrotic diseases and cancer." (PMID 35314685, 2022). "Its frequent expression in malignant tumors suggests that FAP-targeted therapy may be a very attractive strategy." (PMID 35186170, 2022). "Given the ubiquitous nature of fibroblasts in cancer and the avidity of FAP-targeted imaging agents, FAP-targeted PET imaging may significantly change the landscape of oncological PET imaging." (PMID 35626272, 2022). "In several cancer types, high FAP expression is related to poor prognosis." (PMID 36428657, 2022). "FAP overexpression may be positively correlated with GPx4, which consequently inhibits cancer cell ferroptosis." (PMID 36422541, 2022). "In addition, the infiltration of FAP+ fibroblasts was promoted at the late cancer stage and was higher in patients with MSI-H in the TCGA CRC cohort." (PMID 35365629, 2022). "Furthermore, the emerging development of nanoparticle conjugates and antibody-conjugates is offering a potentially wide range of therapeutic options from the perspective of targeting FAP in cancer." (PMID 36263225, 2022). "The correlation between FAP and immune checkpoint genes could be evaluated based on the expression of more than 40 immune checkpoint genes generally found in different kinds of cancers." (PMID 35359436, 2022). "The FAP inhibitor (FAPi) is currently being tested as a cancer therapeutic in clinical trials." (PMID 35565232, 2022). "Notably, we found that both cancer cells and CAFs had high expression of FAP and CREB3L1 in ATC tissues." (PMID 36192735, 2022). "An alternative FAP-directed cancer therapy consists of FAP-mediated activation of prodrugs." (PMID 35158891, 2022). "However, FAP can be used as a target structure by radiolabeled FAP-ligands for diagnostics by positron emission tomography in malignant tumors and myocardial injury." (PMID 36568546, 2022). "The FAP-high subgroup could regulate cancer invasion and immunomodulation, whereas the FAP-low group could regulate glucose homeostasis and lipid metabolism." (PMID 36185262, 2022). "Also, only a mild anti-cancer response was observed in presence of ICs and BFs upon FAP-IL2v monotherapy compared to DP47-IL2v." (PMID 36085201, 2022). "FAP was expressed across all cancer types with variable intensity and frequency." (PMID 34740953, 2022). "PSMA and FAP are two abundantly expressed biological targets on cancer." (PMID 35337180, 2022).